ING5 (inhibitor of growth family member 5)
Description:
Component of the HBO1 complex, which specifically mediates acetylation of histone H3 at 'Lys-14' (H3K14ac) and, to a lower extent, acetylation of histone H4. Component of the MOZ/MORF complex which has a histone H3 acetyltransferase activity. Through chromatin acetylation it may regulate DNA replication and may function as a transcriptional coactivator. Inhibits cell growth, induces a delay in S-phase progression and enhances Fas-induced apoptosis in an INCA1-dependent manner.
Synonyms: FLJ23842; p28ING5
Tractability: PROTAC: ubiquitination databases record sites on it.
Gene: Protein-coding gene on chromosome 2 (241,687,085 to 241,729,481, forward strand). Ensembl gene ENSG00000168395.
Subcellular location: Nucleus; Chromosome
Pathways (Reactome):
Chromatin organization: HATs acetylate histones
Gene Ontology:
Molecular function: histone H3K4me3 reader activity; protein binding; chromatin binding
Biological process: DNA replication-dependent chromatin disassembly; negative regulation of cell population proliferation; negative regulation of growth; positive regulation of apoptotic process; protein acetylation; regulation of cell cycle; regulation of cell growth; regulation of DNA biosynthetic process; regulation of DNA replication; regulation of DNA-templated transcription; positive regulation of apoptotic signaling pathway; regulation of developmental process; regulation of hemopoiesis
Cellular component: chromosome; histone acetyltransferase complex; MOZ/MORF histone acetyltransferase complex; nucleoplasm; nucleus
Genetic constraint (gnomAD): Loss-of-function variants: 13 observed, 31.59 expected, observed/expected ratio (o/e) 0.41, 90% interval 0.27 to 0.65. The upper end of that interval is the gene's LOEUF score, 0.65, which puts it in group 2 of 6, group 1 being the genes least tolerant of losing a copy. Missense variants: 212 observed, 297.11 expected, observed/expected ratio (o/e) 0.71, 90% interval 0.64 to 0.8. Synonymous variants: 118 observed, 114.31 expected, observed/expected ratio (o/e) 1.03, 90% interval 0.89 to 1.2.
Homologues: Orthologues: macaque ING5 (100% identical), dog ING5 (98% identical), pig ING5 (98% identical), mouse Ing5 (95% identical), rabbit ING5 (93% identical), guinea pig ING5 (87% identical), rat Ing5 (81% identical), zebrafish ing5a (78% identical), tropical clawed frog ing5 (72% identical), chimpanzee ING5 (68% identical), zebrafish ing5b (67% identical), Drosophila melanogaster Ing5 (59% identical). Paralogues in human: ING4 (73% identical), ING3 (40% identical), ING2 (39% identical), ING1 (39% identical).
Diseases named in the same sentence as ING5 in open-access papers:
ING5 is named in the same sentence as 57 diseases in open-access papers, as found by Europe PMC text mining. Sharing a sentence is not in itself a finding about the gene and the disease. The quoted sentences say what the papers report.
lung carcinoma (16 papers, 2015 to 2025). "Accordingly, ING5 also inhibits EMT since the loss of ING5 expression in lung cancer enhanced migration and invasion through activation of EGFR/PI3K/AKT and IL-6/STAT3 signalling pathways, which led to the induction of EMT." (PMID 34685579, 2021). "ING5 overexpression also caused chemoresistance in neuroblastoma, glioma, gastric cancer, lung cancer, ovarian cancer and breast cancer cells." (PMID 33425768, 2020). "Taken together, these results indicate that loss of ING5 promotes lung cancer invasion by inducing EMT." (PMID 28903339, 2017). "ING5 overexpression increased glycolysis and subsequent aerobic oxidation of lung cancer cells, which was closely linked to PFK-1 and PDPc overexpression." (PMID 29262575, 2017). "Taken together, these results demonstrate that loss of ING5 enhances aggressiveness of lung cancer cells by promoting EMT via activation of EGFR/PI3K/Akt and IL-6/STAT3 signaling pathways." (PMID 28903339, 2017). "ING5 mRNA levels was significantly higher in normal tissue than lung cancer (p < 0.05), and negatively associated with tumor size of lung cancer (p < 0.05)." (PMID 27409347, 2016). "As early and frequent metastasis is the major cause for high mortality of lung cancer patients, the current data propose ING5 as a biomarker and potent target for anti-metastasis therapy of lung cancer." (PMID 25938545, 2015). "In lung cancer cells, ectopic ING5 expression caused G2 phase arrest and suppressed proliferation, while the overexpression of Cdc2 protein might be attributed to the higher proportion of cells in G2 phase." (PMID 27409347, 2016). "Furthermore, nuclear ING5 was negatively correlated with lymph node metastasis and cancer staging, and was closely linked to better prognosis of lung cancer patients." (PMID 25938545, 2015). "In lung cancer, ING5 overexpression inhibits the epithelial-to-mesenchymal transition (EMT) by promoting phosphorylation‐dependent degradation of β‐catenin, leading to downregulation of WNT/β‐catenin signaling." (PMID 39787145, 2025). "ING5 inhibited tumor growth, blood supply or lung metastasis of gastric, colorectal, ovarian, breast or lung cancer cells by suppressing proliferation, and inducing autophagy and apoptosis in nude xenograft models." (PMID 36425530, 2022). "In lung cancer, ING5 protein was distinctly expressed in small cell carcinoma < large cell carcinoma < adenocarcinoma < squamous cell carcinoma." (PMID 36425530, 2022). "In a recent analysis, insight into the mechanism of action of ING5 in lung cancer is provided, with special emphasis on epithelial-to-mesenchymal-transition (EMT) which is a crucial step for tumor metastasis." (PMID 31390718, 2019). "In a study from 2019 ING5 was found to inhibit lung cancer invasion and EMT via the WNT/beta-catenin pathway." (PMID 31390718, 2019). "Treatment resulted in an inhibition of ING5-knockdown mediated proliferation, colony formation, migration and invasion in the lung cancer A549 cell lines." (PMID 31390718, 2019). "Our results provide mechanistic insights into suppressed invasiveness of lung cancer cells by ING5 overexpression, where ING5-promoted p300 autoacetylation and HAT activity plays an important role." (PMID 29416718, 2018). "The aim of the study was to use integrated approach involving SILAC labeling and mass spectrometry-based quantitative proteomics to quantify dynamic changes of acetylation regulated by ING5 in lung cancer cells." (PMID 29416718, 2018). "ING5 increased H3K18 acetylation supports what we have previous reported that higher nuclear ING5 level predicts a better prognosis in lung cancer patients." (PMID 29416718, 2018).
lung carcinoma (continued). "Previously, we have shown that ING5 inhibits invasiveness of lung cancer cells by downregulating EMT-inducing genes." (PMID 29416718, 2018). "ING5 knockdown also significantly accelerated lung cancer cells to invade through Matrigel-coated polycarbonate filter in the transwell chamber." (PMID 28903339, 2017). "Knockdown of ING5 promoted migration of lung cancer A549 and H1299 cells as assessed by wound-healing assay and transwell migration assay." (PMID 28903339, 2017). "Our data further establish the role of ING5 as a tumor suppressor in lung cancer progression and metastasis by targeting two oncogenic signaling pathways." (PMID 28903339, 2017). "In the current study, we demonstrate, for the first time, that ING5 knockdown promotes invasion of lung cancer cells by inducing EMT via EGFR/PI3K/Akt and IL-6/STAT3 signaling pathways." (PMID 28903339, 2017). "In the current study, we further confirm that loss of ING5 promotes EMT and cancer invasion, suggesting that downregulation of the tumor suppressor gene ING5 potentiates the invasive ability of lung cancer cells by promoting EMT." (PMID 28903339, 2017). "Overexpression of ING5 in lung cancer A549 and H1299 cells and colorectal cancer HCT116 cells significantly reversed activation of both PI3K/Akt and STAT3 pathways." (PMID 28903339, 2017). "Consistent with the results in gastric and lung cancer cells, ING5 mediated chemoresistance of glioma cells to various anti-tumor drugs, which paralleled with apoptotic resistance." (PMID 28915612, 2017). "ING5 suppressed tumor growth and metastasis of lung cancer cells, promoted cell apoptosis and restricted proliferation of hepatocellular carcinoma cells, and significantly inhibited cell migration, invasion, and EMT of breast cancer cells." (PMID 29137236, 2017). "ING5 overexprssion was demonstrated to promote glucose catabolism and fat accumulation in lung cancer cells by up-regulating the expression of ADFP, PFK-1, PDPc and HXK1." (PMID 28915612, 2017). "Our previous study has shown that ING5 overexpression inhibits lung cancer aggressiveness via suppressing epithelial to mesenchymal transition (EMT)." (PMID 28903339, 2017). "ING5 increased glycolysis and aerobic oxidation, which was closely linked to PFK-1 and PDPc hyperexpression in lung cancer cells." (PMID 29137236, 2017). "Previously, nuclear ING5 expression was positively correlated with the favorable prognosis of the patients with gastric cancer and lung cancer." (PMID 29262575, 2017). "Recently, we and others have reported that ING5 inhibits lung cancer migration and invasion by preventing EMT, proposing an anti-metastasis role of ING5." (PMID 28903339, 2017). "ING5 suppressed growth and metastasis of lung cancer cells, promoted cell apoptosis and restricted proliferation of hepatocellular carcinoma cells, and inhibited cell migration, invasion, and EMT of breast cancer cells." (PMID 29262575, 2017). "Previously, we have shown that overexpression of ING5 significantly inhibited lung cancer cell invasiveness by preventing EMT." (PMID 28903339, 2017). "Reportedly, ING5 expression was decreased in many malignancies, including breast cancer, bladder cancer, gastric cancer, lung cancer, head and neck squamous cell carcinoma." (PMID 28915612, 2017). "For the inhibiting effect on epithelial-mesenchymal transition (EMT), ING5 inhibited lung cancer aggressiveness, and ING5 suppressed PI3K/Akt in breast cancer." (PMID 28086946, 2017). "ING5 expression was examined in lung cancers, and compared with their clinicopathological parameters." (PMID 27409347, 2016). "Higher ING5 mRNA expression was detected in younger patients (< 60 years) with lung cancer than the counterparts (p < 0.05)." (PMID 27409347, 2016).
lung carcinoma (continued). "Here, it was found that ING5 overexpression in vivo and vitro induced the autophagy of lung cancer cells with ATG13, ATG14 and Beclin-1 overexpression, indicating that ING5-induced autophagy was dependent on Beclin-1 and belonged to canonical pathway." (PMID 27409347, 2016). "The densitometric analysis showed ING5 protein overexpression in normal tissue, compared with lung cancer (p < 0.05)." (PMID 27409347, 2016). "ING5-overexpressing lung cancer cells showed aberrant fat accumulation according to oil red O staining, and enhanced glycolytic and mitochondrial respiration (p < 0.05)." (PMID 27409347, 2016). "ING5 expression level was significantly higher in normal tissue than that in lung cancer at both protein and mRNA levels." (PMID 27409347, 2016). "In the present study, we observed the effects of ectopic ING5 overexpression on aggressive phenotypes of lung cancer cells, and analyzed the relevant molecular mechanisms." (PMID 27409347, 2016). "ING5 mRNA and protein levels were detected in 5 lung cancer cell lines and one normal human bronchial epithelial (HBE) cells." (PMID 25938545, 2015). "Here we show that ING5 overexpression in lung cancer A549 cells inhibited cell proliferation and invasiveness, while ING5 knockdown in lung cancer H1299 cells promoted cell aggressiveness." (PMID 25938545, 2015). "The results showed that the protein level of nuclear ING5 was negatively correlated with T staging (P = 0.02), lymph node metastasis (P = 0.006) and clinical staging (P = 0.024) of lung cancer patients." (PMID 25938545, 2015). "Taken together, these findings uncover an important role for ING5 as a potent tumor suppressor in lung cancer growth and metastasis." (PMID 25938545, 2015). "The present study by tissue array showed that ING5 was found in normal lung and lung cancer tissues in both cytoplasm and nuclei, and lower nuclear ING5 level was seen more frequently in lung cancer tissues than in normal lung tissues." (PMID 25938545, 2015). "The function of cytoplasmic ING5 and the mechanisms by which it correlates with lung cancer need to be further defined." (PMID 25938545, 2015). "The current data provide insights into how ING5 functions as a tumor suppressor in lung cancer proliferation and metastasis, thus propose ING5 as a novel biomarker and potential therapeutic target for lung cancer." (PMID 25938545, 2015). "The expression score of nuclear ING5 was significantly lower in tumor tissues than that in adjacent non-cancerous lung tissues (P = 0.042), while the cytoplasmic ING5 was significantly higher in lung cancer tissues than normal tissues (P = 0.000)." (PMID 25938545, 2015). "In the current study, we have found that ING5 inhibits proliferation and invasion of lung cancer cells in vitro and in vivo." (PMID 25938545, 2015). "Clinical study by tissue microarray showed that nuclear ING5 negatively correlated with clinical stages and lymph node metastasis of lung cancer." (PMID 25938545, 2015). "The correlation between ING5 expression and clinical parameters and prognosis of lung cancer was investigated." (PMID 25938545, 2015). "Our results show that ING5 expression at both mRNA and protein level differs in a broad variety in lung cancer cell lines." (PMID 25938545, 2015). "To further investigate ING5 function in lung cancer, we chose A549 cells and H1299 cells to establish ING5 overexpression (ING5) stable cell line and ING5 knockdown (shING5) cell line, respectively." (PMID 25938545, 2015). "ING5 overexpression also abrogated tumor growth and invasive abilities of lung cancer cells in mouse xenograft models." (PMID 25938545, 2015). "ING5 downregulation was observed in oral squamous cell carcinoma and lung cancer." (PMID 34685579, 2021). "Additionally, ING5 played a suppressive role in proliferation, migration and invasion in lung cancer." (PMID 32308564, 2020). "The authors established A549 and H1299 lung cancer cell lines stably expressing ING5 mRNA." (PMID 31390718, 2019).
lung carcinoma (continued). "Zhang and colleagues have recently investigated in-depth the role of ING5 in lung carcinoma." (PMID 31390718, 2019). "Recently, we have found that ING5 overexpression could inhibit migration and invasion of lung cancer cells by differentially regulating gene transcription, especially preventing expression of EMT-inducing genes." (PMID 29416718, 2018). "Whether p300-mediated cortactin acetylation promoted by ING5 is involved in ING5-suppressed invasiveness of lung cancer cells deserves further validation." (PMID 29416718, 2018). "Some studies reported that the decreased ING5 protein and its cytoplasmic translocation were observed in many tumors, including bladder cancer, lung cancer, oral squamous cell carcinoma, head and neck squamous cell carcinoma, colorectal, pancreatic cancer, gastric carcinoma and ameloblastoma." (PMID 28086946, 2017). "ING5 overexpression might reverse the aggressive phenotypes of gastric, breast and lung cancer cells, such as proliferation, migration, invasion, epithelial-mesenchymal transition (EMT), growth or metastasis." (PMID 29262575, 2017). "ING5 overexpression might reverse the aggressive phenotypes of gastric, breast and lung cancer cells, including proliferation, migration, invasion, epithelial to mesenchymal transition (EMT), tumor growth or metastasis." (PMID 29137236, 2017). "In line with MET induction of ING5 in lung cancer, and glioma, ING5 overexpression was demonstrated to markedly decrease the ability of breast cancer cells to migrate and invade with E-cadherin overexpression and N-cadherin hypoexpression at both mRNA and protein levels." (PMID 29137236, 2017). "Here, ING5 mRNA and protein were found to decrease in lung cancer, compared with those of normal lung tissues, indicating that its deregulation might promote lung tumorigenesis." (PMID 27409347, 2016). "Taken together, our data suggested that ING5 downregulation might involved in carcinogenesis, growth, and invasion of lung cancer and could be considered as a promising marker to gauge the aggressiveness of lung cancer." (PMID 27409347, 2016). "ING5 expression became gradually weaker from Sq, Ad, LCC to SCC, suggesting that ING5 might be employed as a marker to differentiate the histological subtypes of lung cancer." (PMID 27409347, 2016). "We found that ING5 overexpression not only inhibited proliferation, migration, and invasion, but also induced G2 arrest, differentiation, autophagy, apoptosis, glycolysis and mitochondrial respiration in lung cancer cells." (PMID 27409347, 2016). "The positive relationship between nuclear ING5 and ki-67 (a proliferative marker) expression might be due to a feedback overexpression of nuclear ING5 in lung cancer." (PMID 27409347, 2016). "Finally, we observed the effects and mechanisms of ING5 expression on the growth of lung cancer cells using nude mice model." (PMID 27409347, 2016). "We for the first time reported that ING5 might induce glucose catabolism and aberrant fat deposition in lung cancer cells." (PMID 27409347, 2016). "Survival analysis was performed to identify whether ING5 has prognostic role in lung cancer patients." (PMID 25938545, 2015). "The mechanisms mediating the translocation of ING5 during lung cancer initiation and progression are unknown, which may include protein-protein interaction and post-translational modifications (PTMs)." (PMID 25938545, 2015). "The current results suggest that ING5 could inhibit lung cancer metastasis by preventing EMT through downregulating EMT-inducing genes." (PMID 25938545, 2015). "ING5 is differentially expressed in the observed lung cancer cell lines." (PMID 25938545, 2015). "To investigate whether PI3K/AKT and STAT3 signaling pathways were involved in ING5 knockdown-stimulated lung cancer invasiveness in vivo, we made intravenous mouse xenograft model by injecting A549 shControl and A549 shING5 cells through tail veins of nude mice." (PMID 28903339, 2017).